CD44 (CD44 molecule (IN blood group))
Diseases named in the same sentence as CD44 in open-access papers (continued):
Sharing a sentence is not in itself a finding about the gene and the disease.
prostate carcinoma (continued). "Knockdown of CD44 or FUT1 genes dramatically reduced F77-induced apoptosis in prostate cancer cell lines." (PMID 29423071, 2018). "The model prostate cancer cell line PC3 used in our study proved to be CD44+ and CD133-, as shown by other authors." (PMID 30498638, 2018). "CD44, a major cell surface hyaluronic acid receptor, is involved in invasion, metastasis and drug resistance in many human malignancies including prostate cancer." (PMID 29108245, 2017). "It was reported that the CD133+ cancer-initiating population and CD44+CD24- putative PCSCs in prostate cancer cell lines are AR+." (PMID 28400729, 2017). "By contrast, in prostate cancer, the mechanism is involved in the activation of ERG, depletion of PTEN, and CD44 variant splicing." (PMID 28118608, 2017). "The cell surface markers, CD133 and CD44, are commonly used to isolate prostate cancer cells enriched for CSCs." (PMID 28415604, 2017). "To address this, we examined the expression of three reported prostate cancer stem cells markers, CD44, CD24 and Integrin α2β1, by the OPCT-1 clones." (PMID 28094783, 2017). "The aim of this work was to analyze the enhancement of the anticancer effect of TRAIL by paclitaxel, cabazitaxel and docetaxel in the whole population of PC3 and DU145 prostate cancer cells, but also in CD44+/CD24− prostate cancer stem cells." (PMID 28758908, 2017). "Both NANOG and CD44 expression levels have been shown to correlate in human PC3 prostate cancer cells." (PMID 29156833, 2017). "Their studies showed that CD44+α2β1hiCD133+ cells isolated from prostate cancer patients have a high potential for self-renewal and proliferation; these cells were also able to differentiate to heterogeneous cancer cells in ex vivo culture." (PMID 28400729, 2017). "Taken together, it was possible that CD44 regulates prostate cancer proliferation, invasion and migration via PDK1 and PFKFB4." (PMID 29029419, 2017). "Further, when we reversed the experiment and selected using MACS techniques CD44 positive prostate cancer cells, the immunofluorescent analysis demonstrated that practically 100% of CD44+ cells express TF-Ag." (PMID 29228713, 2017). "CD44 is a direct and functional target of miR-34a, suggesting the key regulatory role of miRNAs in the development of CSCs in prostate cancer." (PMID 28783103, 2017). "In prostate cancer, miR-34a negatively regulates CD44 to inhibit cancer regeneration and metastasis." (PMID 29037220, 2017). "In fact, it has been previously reported that hsa-miR-24c-3p shows stability in CD44+ and CD44− prostate cancer cell subpopulations." (PMID 28051134, 2017). "Here, combined RNA-seq and ChIP-seq analysis reveals that REST is involved in epithelial-mesenchymal transition (EMT) and stemness acquisition in NE differentiated prostate cancer (PCa) cells via direct transcriptional repression of Twist1 and CD44." (PMID 28256535, 2017). "Here, the authors demonstrate the tumor-suppressive functions of miRNA141 in prostate cancer stem cells mediated by directly targeting CD44, Rho GTPase protein family members, and EZH2." (PMID 28112170, 2017). "CD44+ cancer cells display an aggressive phenotype, and CD44 is a cancer stem cell marker in prostate cancer." (PMID 29050362, 2017). "For example, the CD44+α2β1+CD133+ cells purified from human prostate tumor samples, the CD44+ cells in several prostate cancer xenografts, and the BCRP+ putative PCSCs are all AR-." (PMID 28400729, 2017). "CD44 is a glycosylated protein highly expressed at the cell surface of breast, ovarian and prostate cancer cells including cancer stem cell (CSC)." (PMID 28465354, 2017). "Switch from CD44+ cell to EMT cell is regulated by TGF-β1-CD44 signaling as a critical step in prostate cancer cell metastasis." (PMID 29108245, 2017). "For example, microRNA-34a inhibits prostate cancer stem cells and metastasis by directly repressing CD44, while miR-203 suppresses tumor growth and angiogenesis by targeting VEGFA in cervical cancer." (PMID 28030804, 2017).
prostate carcinoma (continued). "Our recent studies have shown that CD44, a cell-surface protein with functions in many biologic processes, involved in glucose metabolism of prostate cancer cells." (PMID 29029419, 2017). "African-American prostate cancer patients were also found to have higher rates of methylation of the CD44 gene, which was downregulated in malignant RC-77 T/E cells in this study." (PMID 28697756, 2017). "CD44 signaling in prostate cancer cells has also been shown to regulate key proteins (i.e., RANKL and MMP9) involved in osteoclast differentiation and tumor metastasis." (PMID 28326306, 2017). "The switch from standard CD44 to CD44v6 improved survival and adhesion in prostate cancer (PC3) cells." (PMID 28326306, 2017). "Systemic delivery of miR-34a, which is known to target CD44 and is usually repressed in prostate cancer, inhibited metastasis of prostate cancer cells and prolonged survival of mice." (PMID 27766946, 2016). "In prostate cancer cells, RBM3 represses the variant v8–v10 of CD44 mRNA to inhibit stemness and tumorigenesis but enhances the standard spliced CD44 transcript." (PMID 27147467, 2016). "Pten knockdown in DU145 prostate cancer cells yields an enrichment in CD133+/CD44+ CSCs, while treatment with LY294002 reduces sphere formation." (PMID 26880966, 2016). "To assess this possibility, we collected whole cell lysates from DU145 and PPC1 cells expressing NT or Arl8b shRNA and probed for prostate cancer stem cell markers, CD44 and ALDH1A1, by immunoblot." (PMID 27105540, 2016). "In particular, the fact that prostate cancer stem cells (CD44+/CD133+/α2β1+) share antigenic properties with prostate stem cells (CD133+/α2β1+) supports the idea that they arise from the normal stem/progenitor cell counterpart." (PMID 26880966, 2016). "CD44 is required for Shh signalling pathway activation in various types of cancer, including ovarian, pancreatic, and prostate cancers." (PMID 26839535, 2016). "ALDH alone was also used as an expression marker in both breast and prostate cancer to identify a distinct population of stem-like cells in addition to the CD44+/CD24- fraction." (PMID 27457474, 2016). "In breast and prostate cancer in particular, the subpopulation of cancer cells with stem-like properties is identified as being enriched in the CD44+/CD24- fraction." (PMID 27457474, 2016). "CD44 is a marker of prostate cancer stem cells, miR-34a inhibits CSCs and cancer metastasis by targeting CD44." (PMID 26349457, 2016). "We showed that miR-708 is a key negative regulator of the CD44(+) subpopulation of prostate cancer cells by directly regulating CD44." (PMID 27588490, 2016). "In this study, we characterized the biological functions of miR-199a-3p in CD44+ prostate cancer (PCa) cells and in tumor regeneration." (PMID 27447749, 2016). "Our finding is consistent with another report that CD44+ prostate cancer cells are highly tumorigenic and metastatic." (PMID 25483103, 2015). "Liu and colleagues first demonstrated that miR-34a levels were reduced in CD44+ prostate cancer cells." (PMID 26231042, 2015). "Insertion of phosphorylated Ser325 (pSer325) or pSer323 and pSer325 in the peptides disrupted the activation of CD44/MMP-9 signaling complex in prostate cancer cells." (PMID 25999946, 2015). "It has been previously shown that a CD44+/α2β1high/CD133+ phenotype represent the candidate prostate cancer tumorigenic cells." (PMID 26485709, 2015). "This Registered report describes the proposed replication plan of key experiments from ‘The microRNA miR-34a inhibits prostate cancer stem cells and metastasis by directly repressing CD44’ by Liu and colleagues published in Nature Medicine in 2011." (PMID 26231042, 2015). "In this study, we show CD44, in response to TGFβ1, regulates the mesenchymal phenotype in prostate cancer cells." (PMID 25483103, 2015).
prostate carcinoma (continued). "It has been revealed that the tumorigenic prostate cancer stem cells can express specific markers such as telomerase, CD44, CD133, α2β1-integrin, multidrug resistance proteins, aldehyde dehydrogenase, and low or undetectable levels of AR." (PMID 26593898, 2015). "In breast and prostate carcinoma, CD44 is commonly used as a surface marker to identify cancer stem-like or progenitor cells, i.e. tumor cells with self-renewal potential." (PMID 26189059, 2015). "In silico analysis of FYN expression in prostate cancer cell line databases revealed an association with the expression of neuroendocrine (NE) markers such as CHGA, CD44, CD56, and SYP." (PMID 26624980, 2015). "Chlorin e6 (Ce6), a photosensitizer, was conjugated to CD44 antibody in order to target PC-3, a prostate cancer cell line." (PMID 26011055, 2015). "mir-34a has also been previously demonstrated for targeting stem cell marker CD44 in prostate cancer and also playing a role in NF-κB pathway in esophageal cancer." (PMID 26579204, 2015). "CD44 has been identified to be the direct target of miR-34a in prostate cancer, bladder cancer and renal cancer." (PMID 25551284, 2014). "CD44 is a surface adhesion molecule and it has been identified as the prostate cancer and cystic cancer stem cell marker, and emerged as an important gene in multiple aspects of cancer development and progression." (PMID 25551284, 2014). "Up-regulation of miR-34a leads to an inhibition of sphere formation and tumor progression in prostate cancer cells and in CD44+ cell." (PMID 24618337, 2014). "According to the previous study in prostate cancer dual luciferase reporter assay was used and determined CD44 was also exactly the target of miR-34a in bladder cancer cells." (PMID 25551284, 2014). "CXCR7 has been reported to influence adhesion in multiple cell types and can specifically regulate cadherin 11 and CD44 in prostate cancer cells." (PMID 25084358, 2014). "Prostate cancer stem cells have previously been isolated and characterized by a CD44+/CD133+/α2β1hi phenotype." (PMID 24465715, 2014). "Holoclones formed by the prostate cancer cell line PC-3 are highly tumorigenic, can be passaged long term and express the cancer stem cell markers α2β1+ CD44+." (PMID 24587067, 2014). "CD44+ prostate cancer cells are purified from xenografts in mice and primary tumors in humans as prostate CSCs." (PMID 24618337, 2014). "High expression of CD44 was observed on the surface of skin, cervix, endometrium, stomach, colon and prostate cancer cells." (PMID 23445749, 2013). "Evidence of CD44 involved in prostate cancer is conflicting as some have shown increased expression of CD44s and CD44 variants to be associated with poor prognosis." (PMID 23476138, 2013). "The CTCs identified with GLV-1h254 in mice bearing human PC-3 prostate cancer xenografts displayed high levels of the expression of the CSC markers CD44 and aldehyde dehydrogenase 1 (ALDH1) as well as the EMT markers vimentin and N-cadherin." (PMID 24019862, 2013). "A recent study has revealed that miR-34a inhibits prostate cancer stem cells and metastasis by directly repressing CD44." (PMID 23383988, 2013). "Further, the microRNA miR-34a inhibits prostate cancer stem cells and metastasis by directly repressing CD44 indicating direct role of CD44 and mir-34a in cancer development and progression." (PMID 24019906, 2013). "In specimens of human Stage I prostate cancers, 0.1% of cells expressed prostate cancer stem/progenitor-like cell markers, including CD44, CD133, CK5/14 and integrin α2β1." (PMID 24086346, 2013). "Studies have shown a suppressive effect on N-myc expression in neurobalstoma and CD44 in prostate cancer, supporting a role in cancer suppression." (PMID 24019906, 2013). "Over all data from several investigators indicated that origin of prostate cancer can be from basal stem cell population, which expresses CD44(+), α2β1high, CD133(+), ALDHhigh, and other normal basal stem cell markers." (PMID 23936768, 2013).
prostate carcinoma (continued). "The role of CD44 in prostate cancer development and progression remains obscure and needs further elucidation." (PMID 23476138, 2013). "Adhesion of breast and prostate cancer cells to the bone marrow endothelial cell line is directly related to the surface expression of the hyaluronic acid (HA) receptor CD44 which is a transmembrane glycoprotein." (PMID 23476138, 2013). "By blocking CD44 expression, miR-34a inhibited migration and invasion in prostate cancer stem cells." (PMID 23951060, 2013). "Numerous scholars have indicated that prostate cancer cells with the CD133+/CD44+ phenotype demonstrate certain stem cell characteristics, including renewal, multi-potential differentiation, unlimited proliferative capacity and permanency." (PMID 23426586, 2013). "We and others have confirmed that this CD133+/CD44+ cell population makes up a subset of prostate cancer cells that are self renewing, differentiate into heterogeneous tumors, and are highly tumorigenic in immunodeficient mice." (PMID 22359577, 2012). "We and others have demonstrated that CD133+/CD44+ cells from established prostate cancer cell lines are also self-renewing and multipotent, and have strong tumorigenic potential in vivo." (PMID 22359577, 2012). "Prostate cancer progenitor populations can be defined by the expression of cell surface markers CD44, CD133, and α2β1high integrin." (PMID 22359577, 2012). "We confirmed increased expression of CXCR4 in prostate cancer cells grown under sphere forming conditions compared to monolayer conditions, and in CD44+/CD133+ prostate tumor initiating cells compared to CD44−/CD133− cells." (PMID 22359577, 2012). "In one study, systemic delivery of miR-34a inhibited prostate cancer metastasis and extended survival of tumor-bearing mice, in part through targeting of CD44." (PMID 22505930, 2012). "Although it has been examined in several studies, the expression and function of the HA receptor, CD44, in prostate cancer invasion and in the LNCaP series of cell lines has failed to lead to general consensus." (PMID 23166824, 2012). "Another more recent pre-clinical study, identified and validated miR-34a as a novel therapeutic agent against prostate cancer stem cells (CSCs) by direct functional targeting of CD44 cells." (PMID 22312290, 2012). "Taken together, these results indicate that salinomycin decreases ALDH activity and CD44+ cancer stem cell fraction in cultured prostate cancer cells." (PMID 22215106, 2012). "CD44 was reported as a metastasis suppressor for some prostate cancers, and the expression of the standard form of CD44 decreased during the progression of prostate cancer to a metastatic state." (PMID 22895640, 2012). "This increased level of CXCR4 expression in the CD133+/CD44+ cell population suggests an important role for CXCR4 signaling in the maintenance of prostate cancer progenitors." (PMID 22359577, 2012). "The present study was performed to evaluate the role of CD44 in prostate cancer-induced bone metastasis." (PMID 22966907, 2012). "We then tested the effects of the CXCR4-specific small molecule antagonist AMD3100 on the survival of the progenitor population (CD44+/CD133+) within prostate cancer cell lines." (PMID 22359577, 2012). "Our purpose in the study was to investigate the effects of down-regulation of CD44 or CD147 on the metastatic ability of prostate cancer (CaP) cells, their docetaxel (DTX) responsiveness and potential mechanisms involved in vitro and in vivo." (PMID 22870202, 2012). "Our data suggest that CXCL12 regulates the adhesion of CD133+/CD44+ prostate cancer progenitors to the extracellular protein fibrionectin which is important for distal organ seeding and initiation of secondary tumors." (PMID 22359577, 2012). "To address this issue, we isolated a rare tumor cell population on the basis of its CD44+CD24− phenotype from the human androgen-independent prostate carcinoma cell line DU145 and established its CSC properties." (PMID 22328933, 2012).
prostate carcinoma (continued). "The results indicated that salinomycin reduced the amount of CD44+ cells in all prostate cancer cells tested already after 6-h exposure." (PMID 22215106, 2012). "Salinomycin impacted on prostate cancer stem cell functions as evidenced by reduced aldehyde dehydrogenase activity and the fraction of CD44+ cells." (PMID 22215106, 2012). "As NF-κB and ALDH activities as well as CD44+ cell population have all been previously shown to regulate prostate cancer cell migration, the migratory effect of salinomycin was studied in prostate cancer cells." (PMID 22215106, 2012). "To verify that CXCR4 expression is upregulated in prostate tumor initiating cells, we examined CXCR4 levels in CD44+/CD133+ prostate cancer progenitor cells and total cell populations in the DU145 and PC3 cell lines by flow cytometry." (PMID 22359577, 2012). "With regard to prostate cancer progression, CD44 has been reported to be on the population of tumor cells enriched in tumorigenic potential." (PMID 24212937, 2011). "The ALDH+ population of LNCaP-IL6 cells had a high expression of the putative prostate cancer stem cells markers CD44 and integrin α2β1 compared to the ALDH− population." (PMID 21779382, 2011). "CD44 expression also appeared to be dichotomous as reflected by the presence of high and intermediate staining populations within the prostate cancer cell lines." (PMID 24212937, 2011). "In accordance with the cancer stem cell models that posit only a rare subset of cells are tumor-initiating cells, several markers for prostate cancer stem cells have been reported including the cell surface markers CD44 and CD133." (PMID 24212937, 2011). "A CD44+α2β1CD133+ population of cells was previously characterized as a stem cell in primary and metastasized prostate cancers." (PMID 24212937, 2011). "Treatment of prostate cancer cells with a neutralising CD44 antibody decreased cancer cell adhesion to human bone endothelial cells, a primary site for prostate cancer cell metastasis." (PMID 21541039, 2011). "A racial difference in the methylation status of the GSTP1, CD44, ESR, and CDH1 genes is associated with prostate cancer." (PMID 20671914, 2010). "Since CSCs has been successfully isolated from established human cancer cells lines, we examined the effects of EGCG on cancer stem cells (CD44+CD133+) isolated from human prostate cancer cell lines." (PMID 20718984, 2010). "Our data indicate that human prostate cancer cell lines contain a small population of CD44+CD133+ cancer stem cells and their self-renewal capacity is inhibited by EGCG." (PMID 20718984, 2010). "Integrin αvβ3 and CD44 have a role in the metastasis of prostate cancer cells to bone by arbitrating adhesion to and migration on OPN protein present in the bone microenvironment." (PMID 20868520, 2010). "In respect to the down-regulation of CD44 during progression and metastasis of prostate cancer, CD44 is a metastasis suppressor for this tumour type." (PMID 20565761, 2010). "Examination of human prostate cancer cell lines and xenografts indicate that the CD44+ population is more proliferative, clonogenic, tumorigenic, and metastatic than CD44- cells." (PMID 20718984, 2010). "In prostate cancer, innovative studies have led to the identification of CD44+/α2β1high/CD133+ prostate cancer stem cells." (PMID 20718984, 2010). "Prostate cancer cells in primary tumors have been typed CD10-/CD13-/CD24hi/CD26+/CD38lo/CD44-/CD104-." (PMID 20021671, 2009). "Here, we identify a rare subpopulation of CD44+CD24− prostate cancer cells with stem-like characteristics such as increased clonogenic and tumorigenic properties, and the ability to grow as nonadherent spheres in serum-replacement medium." (PMID 18268494, 2008). "CD44+ from immortalised prostate cancer cell lines formed colonies in soft agar and tumours in NOD/SCID mice." (PMID 18268494, 2008).